CLCN1 (chloride voltage-gated channel 1)
Diseases named in the same sentence as CLCN1 in open-access papers (continued):
Sharing a sentence is not in itself a finding about the gene and the disease.
Myotonia (continued). "CLCN1-myotonias are usually characterized by a warm-up phenomenon, worsening of myotonia under low temperature environment, and more prominent myotonia at lower limbs." (PMID 33263785, 2021). "Focusing on muscle, an aberrant regulation of RNA-binding proteins causes splicing alterations in the voltage-gated chloride channel 1 (CLCN1) transcript resulting in myotonia with delayed muscle relaxation in skeletal muscle cells." (PMID 33255644, 2020). "DM1 is caused by a pathogenic CTG expansion in DMPK (>50 repeats) which results in altered splicing of CLCN1, as well as other genes, leading to reduced chloride conductance and myotonia." (PMID 32670189, 2020). "Rescue of CLCN1 mis-splicing is sufficient to improve myotonia, and thus can serve as a therapeutically-relevant read-out in small molecule screens." (PMID 31426500, 2019). "Our report further highlights the potential contribution of this gene, together with CLCN1, to the mechanism of the myotonia shown by DM patients." (PMID 30688039, 2019). "One of the primary symptoms of DM—myotonia—results from mis-splicing of the muscle-specific chloride channel (CLCN1) pre-mRNA, leading to a depletion of protein levels." (PMID 31426500, 2019). "In theory, improvement in myotonia should have been accompanied by corrected splicing of the CLCN1 gene." (PMID 30794581, 2019). "In this context myotonia is the consequence of the abnormal splicing of the CLCN1 chloride channel, while insulin resistance is most likely associated with the missplicing of the insulin receptor." (PMID 30050493, 2018). "In congenital myotonia, sexual steroid hormones influence severity of myotonia, reflecting testosterone modulation of CLCN1 chloride channel activity." (PMID 26849574, 2016). "These groups propose that disruptions in alternative splicing regulation of ClCN1 causes a channelopathy and membrane hyperexcitability, leading to the classic DM1 feature of myotonia." (PMID 23938156, 2013). "Because myotonia was more severe following the depletion of Mbnl2, we first compared the Clcn1 splicing pattern in WT, Mbnl1 KO and Mbnl1−/−; Mbnl2+/− KO skeletal muscle." (PMID 24293317, 2013). "Myotonia has been attributed to reduced expression of Clcn1 due to the combined effects of a decrease in transcription from the Clcn1 gene and inclusion of alternative exon 7a, which includes a TGA stop codon that triggers non-sense mediated decay." (PMID 19516957, 2008). "Diverse genes are consequently reduced in expression, including the muscle-specific chlorine channel 1 (CLCN1), which has been involved in myotonia." (PMID 19516957, 2008). "Generation of a Clcn1 exon 7a deletion mouse for elimination of myotonia from DM1 mouse models." (PMID 41000779, 2025). "In people, the non-dystrophic myotonias associated with mutations in the CLCN1 gene produce a wide spectrum of clinical phenotypes with varying degrees of muscle hypertrophy and severity of myotonia." (PMID 38473107, 2024). "In 2018, mexiletine was approved for the symptomatic treatment of non-dystrophic myotonia (paramyotonia congenita and myotonia congenita) caused by mutations in chloride (CLCN1) and skeletal muscle voltage-gated sodium (SCN4A) channels." (PMID 36672104, 2023). "For Clcn1, exon 7a inclusion leads to the presence of a premature stop codon during messenger processing, resulting in a truncated protein and decreased functional CLCN1, which is related to myotonia in DM1." (PMID 37372969, 2023). "Thus, an un-biased RNAseq approach, and subsequent Western blot analysis, confirmed our previous finding that the inhibition of GSK3 is linked to the reduction in myotonia caused by CUG repeats in HSALR mice, via the correction of Clcn1 levels." (PMID 37445828, 2023). "Those with myotonia congenita, hence alterations in the CLCN1 gene, have classical symptoms of muscular involvement, with a classical aspect on examination (a delayed relaxation after the contraction) and improvement of myotonia with activity." (PMID 36983602, 2023).
Myotonia (continued). "It is widely accepted that myotonia in DM1 stems from alterations in the splicing of the CLCN1 chloride channel, which leads to a reduction in functional protein, causing a decrease in chloride conductance and a depolarization in the membrane potentials of muscle fibers." (PMID 37372969, 2023). "Recessive CLCN1 variants in RMC patients lead to loss of function of the mutated subunit, which causes the accumulation of potassium ions and after depolarization bursts, manifesting as myotonia." (PMID 35350395, 2022). "Indeed, PMO injected in combination with bubble liposomes and ultrasound application achieved a greater correction of Clcn1 splicing and a reduction of myotonia." (PMID 36362145, 2022). "Interestingly, a PMO-ASO-mediated approach was applied to correct defective splicing of Clcn1 and led to amelioration of myotonia in HSALR." (PMID 35563013, 2022). "Mis-splicing of CLCN1, a skeletal muscle specific chloride channel which causes myotonia, was not identified since CLCN1 is not yet expressed in these early developmental stages." (PMID 35019138, 2022). "Phenytoin and gabapentin were the most effective therapies in recessive CLCN1-myotonia." (PMID 35170402, 2022). "NDMs are mainly related to the reduced activity of the CLC-1 channels or impaired inactivation of the NaV1.4 channels caused by CLCN1 or SCN4A variants, which lead to sarcolemmal hyperexcitability manifesting as myotonia." (PMID 35350395, 2022). "More than 150 CLCN1 and at least 100 SCN4A myotonia-associated gene variants are currently known." (PMID 33263785, 2021). "To test whether myotonia may contribute to splicing dysregulation, we examined mice with generalized myotonia congenita due to homozygous inactivation of the Clcn1 chloride channel (adr mice)." (PMID 33503262, 2021). "The variant was previously reported in an individual with non-dystrophic myotonia who also carried a second CLCN1 pathogenic variant." (PMID 32466254, 2020). "The high prevalence of reported weakness is particularly notable given that the majority (85%) of our CLCN1 cohort had a single variant identified, and dominant CLCN1-related myotonia has not been classically associated with weakness." (PMID 32670189, 2020). "Weakness was reported in a similar proportion of individuals with non-dystrophic myotonias, 65.2% (n = 15) of individuals with CLCN1 variants, and 69.2% (n = 9) SCN4A variants." (PMID 32670189, 2020). "MVRC analysis suggests that this CLCN1 variant is not silent and contributes to the severe myotonia in the patient." (PMID 31772215, 2019). "Muscle excitability recordings suggest that a concomitant synonymous CLCN1 variant in R222Q patient is not silent, but rather exacerbates myotonia." (PMID 31772215, 2019). "Mutations in the genes encoding voltage-gated Cl− and Na+ channels (respectively, CLCN1 and SCN4A) produce a wide spectrum of phenotypes, which differ in age of onset, affected muscles, severity of myotonia, degree of hypertrophy, and muscle weakness, disease progression, among others." (PMID 32010054, 2019). "Most notably, oral administration of erythromycin in the HSALR DM1 mouse model at the equivalent therapeutic dose currently being used in humans, significantly rescued mis-splicing of several events, including Clcn1 exon 7a and Atp2a1 exon 22, and partially rescued myotonia." (PMID 31426500, 2019). "The proband is a patient affected by a maternally transmitted DM2 with an early and severe myotonia in absence of associated mutations in CLCN1 gene." (PMID 30038349, 2018). "In our study, we investigated a DM2 patient with severe and early onset myotonia without mutations in CLCN1 or SCN4A genes." (PMID 30038349, 2018). "However, in the dog with myotonia from the present study, none of the previously reported mutations in the CLCN1 gene associated with myotonia in dogs or other domestic animals were identified." (PMID 39559538, 2024).
Myotonia (continued). "Most of these mutants have a recessive inheritance in agreement with the general hypothesis that the loss of one CLCN1 allele is not sufficient to cause myotonia." (PMID 37892996, 2023). "CLCN1 or SCN4A mutations lead to the dysfunction of the CLC-1 or NaV1.4 channel, which may predispose the muscle to sarcolemmal hyperexcitability manifesting as myotonia." (PMID 35350395, 2022). "However, at least for NDM6, the patient showed a similar phenotype (including age of onset, no weakness or muscle pain, generalized myotonia, etc.)as patients carrying only the CLCN1 mutation in heterozygosity or the SCN4A mutation." (PMID 33670307, 2021). "Interestingly, the prevalence of stiffness was the only feature that differed significantly among patients with non-dystrophic myotonias, with more individuals with CLCN1 variants reporting this symptom than individuals with SCN4A variants." (PMID 32670189, 2020). "Clinical, genetic and muscle excitability recordings suggest that the synonymous CLCN1 c.1650G>A variant is not functionally silent in our patient, and may act as a modifier to exacerbate the severity of myotonia." (PMID 31772215, 2019). "Therefore, the up-regulation of CELF activity that often accompanies MBNL sequestration in DM skeletal muscle may destabilize the CLCN1 mRNA and exacerbate myotonia symptoms." (PMID 25883322, 2015). "In addition, the quantification of CLCN1 gene transcript in the muscle biopsy of family 1 proband suggests that changes in ClC-1 expression are likely not involved in the determination of myotonia, at least for p.G190S and p.T82A mutations." (PMID 26007199, 2015). "We reviewed T1-weighted and STIR (short-tau-inversion-recovery) 3T MRI sequences of lower limb muscles at thigh and calf level in 21 patients with genetically confirmed non-dystrophic myotonia: 11 with CLCN1 mutations and 10 with SCN4A mutations, and 19 healthy volunteers." (PMID 23810313, 2013). "Mis-spliced ion channels associated with defects in skeletal muscle excitation-contraction coupling and myotonia – CACNA1S e29 and CLCN1 e7a – frequently ranked among the top 3 most significantly correlated events for ADF, HGS, and 10MRW." (PMID 39836447, 2025). "While select CDMadolescent individuals have nearly 100% CLCN1 exon 7a inclusion, like that of their adult DM1 counterparts with the highest vHOTthumb times, minimal myotonia was observed." (PMID 39450929, 2024). "In fact, CDMadolescent individuals who had nearly 100% CLCN1 exon inclusion, like the most severely affected adults with DM1, possessed minimal quantitative myotonia." (PMID 39450929, 2024). "Myotonia at onset was more frequent in patients with CLCN1-myotonia (85.7%) than in patients with SCN4A-myotonia (50%) (p = 0.003); periodic paralysis was only reported in patients with SCN4A-myotonia (20%) (p = 0.008)." (PMID 33263785, 2021). "Discussion: Among the features reviewed, we did not identify clinical or electrophysiological differences to distinguish CLCN1- and SCN4A-related myotonia." (PMID 32670189, 2020). "Of those who trialed medications, 56.5% (n = 13) of CLCN1 patients, 66.7% (n = 10) of SCN4A patients, and 8.3% (n = 2) of DMPK patients had tried more than one medication for myotonia." (PMID 32670189, 2020). "Although painful myotonia is an accepted clinical feature of SCN4A-related myotonia, CLCN1-related myotonia was originally described as being painless." (PMID 32670189, 2020). "In line with this view, compelling evidence has demonstrated the direct role of CLCN1 chloride channel missplicing in the onset of DM1 and DM2 myotonia." (PMID 30050493, 2018). "In particular, DMPK- and ZNF9-induced alteration of CLCN1 transcription have been demonstrated in several mouse models of DM1 and DM2, and is likely responsible for the observed myotonia." (PMID 25964741, 2015).
Myotonia (continued). "The results show that expression of ClC-1 mRNA was similar between MC and control individuals, excluding alterations in CLCN1 expression as a contributor to myotonia in these patients." (PMID 26007199, 2015). "Among the mis-splicing events that have been documented, splicing reversions occurring in the muscle chloride channel CLCN1, the insulin receptor INSR and BIN1 contribute respectively to myotonia, insulin resistance and muscle weakness." (PMID 25211016, 2014). "Perhaps the most surprising finding of these analyses was the observed lack of correlation between [MBNL]inferred or CLCN1/CACNA1S mis‐splicing levels with quantitative measures of myotonia in children with CDM." (PMID 39450929, 2024). "Myotonia in DM1 is attributed to alteration of the splicing of Clcn1 and a reduction in Clcn1." (PMID 37445828, 2023). "To test the hypothesis that deregulated Clcn1 alternative splicing and resulting myotonia are responsible for the fiber type transition in DM1 mice, we injected tibialis anterior (TA) muscles with an ASO that induces targeted skipping of Clcn1 exon 7a24." (PMID 37029100, 2023). "Significant clinical overlap exists between CLCN1 and SCN4A myotonias." (PMID 33263785, 2021). "In patients suspected of having a non-dystrophic myotonia, the most expeditious, and cost-effective approach is panel testing including CLCN1 and SCN4A sequencing." (PMID 32670189, 2020). "It should be noted that the degrees of CLCN1 splicing misregulation in DM2-PDM is similar to that observed in DM2-PROMM despite myotonia in DM2-PDM is not evident at clinical level." (PMID 24376746, 2013). "Therefore, it is reasonable to consider that, even in the absence of patch-clamp studies, the truncated CLCN1 (~400 aa shorter than the normal chloride channel 1) observed in the dog from the present study is responsible for the clinical myotonia." (PMID 39559538, 2024). "Analysis of chloride channel (CLCN1) splicing, another gene misspliced in DM1 which has been implicated in chloride channelopathy and myotonia, revealed no dysregulation in the tibialis anterior (TA) from untreated HSALR mice compared with that from wild-type mice." (PMID 36835205, 2023). "Notably, MBNL1 knockout mice display myotonia due to abnormal CLCN1 splicing and develop myopathy, but exhibit no sign of muscle degeneration." (PMID 25211016, 2014). "Notably, there are a few genes that are misspliced in DM1, and have been linked to a definitive symptomatic outcome, that are misspliced neither in FSHD nor EDMD, namely CLCN1, ATP2A1/2 and MYOM1, of which the CLCN1 missplicing results in the most unique feature of DM1: myotonia." (PMID 40149583, 2025). "Recent studies indicate that, unlike DM1, either CLCN1 or SCN4A acts as genetic modifiers in DM2 patients since mutations/polymorphisms in these genes may contribute to exaggerated phenotype with more severe muscle stiffness and myotonia." (PMID 34234810, 2021). "Nevertheless, the severity of myotonia especially at lower limbs and the general stiffness were not satisfactorily explained by the diagnosis of PMC based on clinical symptoms and genetic analysis of SCN4A, hence the involvement of a second genetic “player,” namely CLCN1 gene, was hypothesized." (PMID 36081873, 2022).
myotonia congenita (78 papers, 2011 to 2025). "The rarity of seizures in patients with myotonia congenita and the low incidence of CLCN1 mutations linked to epilepsy indicate that a direct role of ClC-1 in epilepsy is unlikely." (PMID 40223930, 2025). "Genetic testing reported a homozygous state due to c.1667T>A in exon 15 of the CLCN1 that encodes the ClC-1 protein, the skeletal muscle chloride channel protein responsible for the myotonia congenita." (PMID 40535402, 2025). "Mutations in the CLCN1 gene can lead to partial or complete loss of ClC-1 channel function, a well-known cause of myotonia congenita, thus designating ClC-1 as the skeletal muscle chloride channel." (PMID 40223930, 2025). "The most common channelopathy was myotonia congenita, which was associated with variants in the CLCN1 gene in 10 of the 11 patients, and one was associated with a variant in the SCN4A gene." (PMID 40883749, 2025). "Myotonia congenita, both in a dominant (Thomsen disease) and recessive form (Becker disease), is caused by molecular defects in CLCN1 that encodes the major skeletal muscle chloride channel, ClC-1." (PMID 39712484, 2024). "In this study only a recessive form of myotonia congenita caused by pathogenic variants in the CLCN1 gene was detected." (PMID 38758368, 2024). "Myotonia congenita is an inherited disease in humans and animals caused by genetic variants in the CLCN1 gene." (PMID 39765607, 2024). "This manuscript summarises information about myotonia congenita in humans, companion animals and livestock and describes myotonia congenita for the first time in Merino sheep, associated with a novel variant in the CLCN1 gene." (PMID 39765607, 2024). "To date, myotonia congenita in dogs has been associated with five different variants in the CLCN1 gene (OMIA:000698-9615), including five different breeds." (PMID 38473107, 2024). "Myotonia congenita is caused by pathogenic mutations in genes encoding chloride (CLCN1) and voltage-dependent muscle sodium (SCN4A) channels." (PMID 38672523, 2024). "Another patient diagnosed with myotonia congenita was compound heterozygous for the CLCN1 variants c.2680C > T (p.R894X) and c.264G > A (p.V88V)." (PMID 38055022, 2024). "A thorough clinical and pathologic investigation supported a diagnosis of myotonia congenita in Merino sheep, allowing identification of a functional candidate gene and the identification and validation of the likely causal variant in CLCN1." (PMID 39765607, 2024). "Tests for genetic defects of the CLCN1 gene, known to cause myotonia congenita in other canine breeds, such as American Bulldog, Australian Cattle dog, Jack Russel Terrier, Labrador Retriever, and Miniature Schnauzer were negative." (PMID 37222814, 2023). "Myotonia congenita (MC) is a rare neuromuscular disease caused by mutations within the CLCN1 gene encoding skeletal muscle chloride channels." (PMID 36659963, 2023). "Our cohort comprised 223 probands referred for genetic testing for myotonia congenita in whom CLCN1 variants were identified." (PMID 34529042, 2022). "Myotonia congenita (MC) is a genetic disease caused by mutations in CLCN1 on chromosome 7q35 (OMIM # 118,425), coding for the main voltage-dependent chloride channel CLC-1 in skeletal muscle cells." (PMID 35170402, 2022). "Myotonia congenita is a rare neuromuscular disorder caused by CLCN1 mutations resulting in delayed muscle relaxation." (PMID 36212636, 2022). "Sequencing of CLCN1, the gene that encodes CLC-1, is central to the diagnosis of myotonia congenita." (PMID 34529042, 2022). "Mutations in CLCN1 lead to either the autosomal dominant form or the recessive form of myotonia congenita (MC)." (PMID 36081873, 2022). "Bearing in mind the previously reported cases of cardiac arrhythmias in myotonia congenita patients, we discuss the possible involvement of the CLCN1-gene mutations in primary cardiac arrhythmia." (PMID 36212636, 2022).